BRAF (B-Raf proto-oncogene, serine/threonine kinase)
Diseases named in the same sentence as BRAF in open-access papers (continued):
Sharing a sentence is not in itself a finding about the gene and the disease.
tumor (continued). "Our study extends the current paradigm to imply that patients with KRAS-, BRAF- or PIK3CA-mutant tumours may all derive limited benefit from treatment with EGFR mAb, and that BRAF mutations in particular account for a measurable fraction of patients whose KRASWT tumours do not respond to cetuximab." (PMID 19603024, 2009). "As observed in IPC298 cells, targeting BRAF, CRAF or PIK3CA individually in SK-MEL-30 cells did not effect in vivo tumor growth." (PMID 19492075, 2009). "Moreover, some details about the site of metastases, the duration of response and molecular profile of the tumour such as KRAS, BRAF were not available in the included studies." (PMID 40133691, 2025). "We also did not have access to genetic information (KRAS, BRAF, and MSI), which may influence tumor responses to neoadjuvant treatment." (PMID 40715570, 2025). "Both BRAF-fused (median TIS 9.28, p = 8 × 10−8) and BRAF V600E (median TIS 8.88, p = 8 × 10−7) LGG, the two most common genomic alterations in pediatric-type LGG, had increased TIS vs non-tumor brain tissue, but did not have significant differences between each other (p = 0.09)." (PMID 38987542, 2024). "BRAF inhibition with encorafenib 6 mg/kg (green curves) did not change tumor growth compared to the sham-treated control mice (black curves), whereas the use of the MEK inhibitor binimetinib (8 mg/kg) significantly diminished tumor growth in all three models." (PMID 38067230, 2023). "However, unlike BRAF-mutant cells, small interfering RNA (siRNA)–mediated KSR1/2 depletion in tumor cells harboring oncogenic RAS induced a potent apoptotic response, indicating that APS-2-79 was not efficiently inhibiting KSR activity." (PMID 36791195, 2023). "The lack of change in GLUT-1 expression in response to BRAF/MEK inhibition in YUMM1.7 xenografts suggest that this reduction in not due to a decrease in glucose uptake by the cells, but potentially to a decrease in the glycolytic activity of the tumor cells." (PMID 35327519, 2022). "Once considering the immunosuppressive effects of the MAPK pathway, it can be hypothesized that BRAF/MEK inhibition, although not designed to target the immune system, influences the tumor-immune microenvironment and anti-tumor immune responses." (PMID 36233289, 2022). "However, early evidence in preclinical data supports that, unlike the BRAF inhibitor, the MEK inhibitor has pleiotropic effects on tumor cells and lymphocytes." (PMID 36428582, 2022).
tumor (continued). "Indeed, tumor cells were positive for CD57 and WT1 and negative for P504S but also showed a partial positivity for CK7 and the immunohistochemical analysis for BRAF VE1 antibody was negative." (PMID 33175195, 2021). "Moreover, there were no data on race, sex, primary site of the tumor, and status of RAS and BRAF genes." (PMID 33541293, 2021). "Third, we did not test other tumor’s driver genes, such as KRAS, ALK, ROS1, and BRAF." (PMID 35096585, 2021). "Our group has previously reported MSI and RAS/BRAF status as well as immune cell score in a subset of this patient series and, therefore, MSI and RAS/BRAF status as well as detailed histopathological tumor characteristics were not addressed here." (PMID 33920665, 2021). "No BRAF-positive patients were identified in this study, whereas 2.6% (1/43) of patients with stage III NSCLC were ROS1-positive; thus, crizotinib was used as per the guidelines as a first-line treatment for tumour recurrence." (PMID 34064047, 2021). "Interestingly, viability of HAP1 cells did not seem to be affected by the knockout of known tumor type-specific oncogenes such as BCR, PIK3CA, KRAS, CTNNB1, or BRAF." (PMID 33228647, 2020). "Furthermore, at least in the metastatic setting, the effect of tumor site on survival seems to be independent of RAS10 and BRAF status." (PMID 30842570, 2019). "Interestingly, investigation of in silico data rather showed a trend towards lower TERT mRNA expression in BRAF-mutant GBM, but not other BRAF-mutant tumor types." (PMID 31391125, 2019). "Additionally, HER2 amplification detected on tissue or on circulating tumor DNA (ctDNA) was identified as a possible mechanism of acquired resistance in HER2 negative, RAS/BRAF WT, patients progressed during anti-EGFR treatment." (PMID 34532592, 2018). "It is interesting to note that the results presented here are more dramatic than other studies which demonstrated that the BRAF inhibitor PLX4720, the precursor derivative of Vemurafenib, only moderately inhibited tumor growth in vivo without inducing tumor regression or preventing relapse." (PMID 28753606, 2017). "No tumour was observed in BRAF KO and BRAF/CRAF KO mice, in agreement with the lack of hyperpigmented phenotype upon early BRAF deletion, thereby confirming the requirement of BRAF for tumour initiation." (PMID 28497782, 2017). "The advantages of MBZ are that 1) it interacts with both the active and inactive forms of BRAF, 2) it binds wild type or mutant BRAF with almost equal affinities, and 3) it has very low affinity for CRAF, and therefore would not be expected to stimulate tumor growth." (PMID 28157711, 2017). "We also determined that tumor-derived HGF, not systemic HGF, may be required to convey resistance to BRAF inhibition in vivo and that resistance could be reversed following treatment with AMG 337, a selective MET inhibitor." (PMID 28147313, 2017). "Thus, patients with intrinsic overexpression of this protein, who are exposed to BRAF inhibitors, respond by producing further excessive amounts of COT and, rather than slowing cellular proliferation, the tumor burden increases." (PMID 29100459, 2017). "This tumor was found to be KRAS and BRAF wild type, and EGFR was not overexpressed." (PMID 26909603, 2016). "However, while co-incubation with cetuximab did not result in a significant increase in COLO320 tumor cell death, a significant increase in killing was seen in four EGFR+ cell lines independent of RAS and BRAF status." (PMID 27314237, 2016).
tumor (continued). "Initially, age at PTC diagnosis, presence of solid pathomorphology and presence of the BRAF or RET/PTC alteration known to trigger PTC were considered for their relationship with the differences in gene expression between ECR and non-ECR tumours by separate three-way analyses of variance." (PMID 26810418, 2016). "Sorafenib is indeed not a specific inhibitor of BRAF and as such the effects may not be mediated by targeting KIAA1549-BRAF in this tumor." (PMID 24422672, 2014). "While some tumors showed polysomy of chromosome 7 (3–5 copies) in a portion of the tumor cells, none of the tumors analyzed by FISH showed BRAF duplication suggesting that this mechanism does not account for the activation of the MAPK pathway observed in BRAF V600E-negative PXA." (PMID 21479234, 2011). "They strongly argue that BRAF-selective inhibitors should not be administered to patients with RAS mutant tumors, because long-term use could accelerate tumor growth." (PMID 20141835, 2010). "While our findings demonstrate that FBL promotes tumor aggressiveness and resistance to chemotherapy, they do not explore whether FBL expression varies across key molecular CRC subtypes such as MSI-H, MSS, or RAS/BRAF-mutant tumors." (PMID 41463151, 2025). "The primary tumor origin was not specified in the standard GPA and the EC-S, while all the others included disease-specific predictors such as the time of primary diagnosis, BRAF gene status, Child–Pugh score, tumor markers such as serum CEA, and neurologic symptoms." (PMID 38254781, 2024). "In other words, tumor biology in mCRPC may not be as aggressive in a patient with only an AR amplification compared to those whose malignancy has multiple GAs that include AR (such as MYC, BRAF, PIK3CA, and others)." (PMID 38450313, 2023). "Importantly, while wild type BRAF does not bind to MST1, the oncogenic mutant BRAFV600E can bind to this tumour suppressor, which could conceivably shut down the anti-oncogenic signal mediated by MST1/2 in several cancer types." (PMID 31963420, 2020). "We evaluated the inhibition profiles obtained after ex vivo exposure of tumour tissue lysates to MAPK inhibitors and found that phosphorylation levels of several kinase substrates differed between patients who were responding and not responding to BRAF inhibition monotherapy." (PMID 32098410, 2020). "Furthermore, tumor markers such as MSI status and BRAF, which have prognostic value, could not be determined." (PMID 30915121, 2019). "Further study, nevertheless, showed solely MDSCs depletion could not re-sensitize tumour cells towards BRAF inhibitor treatment, while combination treatment with immunotherapies anti-CTLA-4 and anti PD-1 elicited tumour cells to immunotherapy-triggered cancer cell death." (PMID 29455663, 2018). "Finally, we demonstrate that local/tumor HGF expression may be required to convey resistance to BRAF inhibition in vivo, observing rescue when HGF is expressed in the tumor microenvironment but not when expressed systemically." (PMID 28147313, 2017). "In addition, we did not collect any information on the RAS and BRAF expression status of the tumors and therefore could not investigate whether any relationship existed between the RAS status of the tumor and the efficacy of fruquintinib." (PMID 28103904, 2017). "Moreover, the combination of PD-1 blockade and short-term dual inhibition of BRAF and MEK could enhance tumor immune infiltration and improved tumor regression, suggesting that a nongenomic mechanism of MAPK inhibitor resistance might mediate cross-resistance to PD-1/PD-L1 blockade therapy." (PMID 29299180, 2017).
cancer (3,247 papers, 2003 to 2026). A tumor composed of atypical neoplastic, often pleomorphic cells that invade other tissues. "Among those significantly increased with BRAF+/−MEKi were 14 of 17 genes of a Th1 signature associated with immunologic rejection of cancer, with GNLY, IFNG, and GBP1 the only genes not represented." (PMID 41514118, 2026). "Although BRAF is frequently mutated across multiple cancer types, its clinical utility as a prognostic biomarker has remained inconsistent in clinical practice, likely due to additional events modulating BRAF signaling pathways." (PMID 41648055, 2026). "Regarding BRAF mutations, the second most common alteration detected in PAs is a substitution of valine in position 600 by glutamic acid, which results in BRAF V600E the most frequent BRAF mutation in human cancers." (PMID 41514664, 2026). "Conversely, the serrated lesion-carcinoma pathway is driven by promoter hypermethylation of genes subsequent to BRAF mutations." (PMID 41488286, 2026). "In conclusion, there is an observed difference in therapeutic response to BRAF inhibitors in patients with different cancers harboring BRAF V600E mutations." (PMID 40869231, 2025). "To provide an update on the identity and relative abundance of BRAF transcript variants in human cancer, here we describe the evolution of their annotation in publicly available repositories of RNA and protein sequences." (PMID 40415485, 2025). "We thus concluded that, in general, atypical BRAF mutations and concomitant additional Ras pathway mutations are likely to be present in the same cancer cells." (PMID 39751654, 2025). "In recent years, the categorization of BRAF mutations has proved to be very useful in understanding BRAF alterations in different cancer indications." (PMID 40664146, 2025). "We report that BRAF‐X1 (currently BRAF‐204) is the predominant transcript variant in human cancer and it is expressed at a higher level than the reference (currently BRAF‐220) variant." (PMID 40415485, 2025). "The limited sample size in our study must be carefully considered, and therefore, any conclusions regarding UBE2K in BRAF-mutated cancer cannot be made." (PMID 40080754, 2025). "BRAF, a serine/threonine kinase located immediately downstream in the Ras signaling pathway, is mutated in approximately 15% of all cancers." (PMID 41367868, 2025). "Specific gene mutations, such as KRAS, NRAS, and BRAF, are known to play a crucial role in the propagation of both cancers." (PMID 40447784, 2025). "Class 1 BRAF (V600) mutations comprise the majority of oncogenic BRAF mutations in most cancer types, including 90% of BRAF mutations found in CRC." (PMID 41294686, 2025). "This stark contrast between CRC and other BRAF-mutated cancer types has been shown to be related to EGFR-mediated reactivation of the MAPK pathway upon inhibition of BRAF." (PMID 41294686, 2025). "Its application to a cancer evolution dataset revealed the genes related to primary BRAF-inhibitor resistance from scRNA-seq data of BRAF-mutated cancer cells." (PMID 40549685, 2025). "The most common activating BRAF mutation in BRAF-associated cancer is the substitution of valine with glutamic acid at the codon 600 (V600E)." (PMID 40943615, 2025). "Despite its broad growth inhibitory activity, ADT-007 displayed exquisite target specificity, as cancer cells with WT RAS but downstream BRAF mutations, as well as cells from normal tissue, were essentially insensitive to ADT-007." (PMID 41008802, 2025). "BRAF mutations are detected across a broad range of cancers and are categorised into three functional classes." (PMID 39950095, 2025). "Another way to inhibit the BRAF-mutated cancer is limiting the downstream components of the pathway." (PMID 40943615, 2025). "With the analysis of sequencing results, 147 FNA samples with BRAF V600E mutation were confirmed with malignant tumors by surgical pathology and 6 samples were benign." (PMID 40586006, 2025).
cancer (continued). "This association was discovered after the biological significance of downregulating PDE5a expression by cancer driver mutations in genes within the RAS/BRAF/MEK/ERK pathway was realized." (PMID 41162377, 2025). "The proto-oncogene BRAF has been identified in a wide range of tumors, with oncogenic BRAF mutations found in approximately 6% of human cancers." (PMID 40492122, 2025). "Continued research and innovation are crucial to improving patient outcomes and addressing the complexities of BRAF mutations in human cancers." (PMID 41646490, 2025). "Cytoplasmic MUC1 positivity in cribriform structures was associated with BRAF mutation and with serrated cancer type." (PMID 41332218, 2025). "Since BRAF is the most common mutation found in cancer patients, BRAF inhibitors have been a targeted therapeutic approach with beneficial effects in many cases." (PMID 41304533, 2025). "Overall, the cancers associated with non-V600E BRAF were nearly all low risk, particularly in cases of isolated BRAF mutations." (PMID 40075589, 2025). "The earliest trial identified in our dataset began in 2012, targeting cancers with BRAF V600 mutations." (PMID 41225614, 2025). "LA dose–response screening at the NCI 60 cancer cells panel identified the high sensitivity of the Malme-3M cell line, which harbors a BRAF V600E mutation." (PMID 39795195, 2025). "BRAF mutations have been identified in multiple malignancies, with the BRAF V600E mutation being the most common mutation type across several cancers." (PMID 40861456, 2025). "We built IsoWorm, a bioinformatic pipeline tailored to discriminate and quantify BRAF variants, and employed it to analyze > 600 cancer cell lines and > 1000 cancer tissue samples." (PMID 40415485, 2025). "Dabrafenib and Vemurafenib function as inhibitors of B-Raf, targeting cancers associated with mutations in the BRAF gene." (PMID 41315179, 2025). "BRAF mutational status is a critical biomarker that informs prognosis and guides personalized treatment strategies across multiple cancers." (PMID 41368991, 2025). "Our understanding of immune checkpoint pathways and the BRAF/CKIT genetic mutations which underpin the pathogenesis of many cancers has revolutionised cancer treatment." (PMID 41295253, 2025). "In 2022, the FDA approved the combination of Dabrafenib (Tafinlar) and Trametinib (Mekinist) for cancers with the BRAF V600E mutation, marking a pivotal advancement in precision oncology." (PMID 40075649, 2025). "The Ser/Thr kinase RAF, particularly BRAF isoform is a dominant target of oncogenic mutations and many mutations have been identified in various cancers." (PMID 39897565, 2025). "Atypical BRAF mutations were associated with longer overall survival than class 1 mutations (HR = 0.25; P = 0.011) but lost this advantage in cancers with additional Ras mutations (HR = 0.94; P = 0.86)." (PMID 39751654, 2025). "Single-Nucleotide Polymorphisms (SNPs)—Precise genotyping of cancer-associated SNPs, such as the BRAF V600E mutation, is performed using RPA-Cas12a or Cas12a/Cas13a systems." (PMID 41149312, 2025). "These include pembrolizumab for MSI-H and TMB-H tumors, larotrectinib and entrectinib for NTRK fusion-positive tumors, and Dabrafenib with Trametinib for BRAF V600E-mutated cancers." (PMID 40075649, 2025). "BRAFV600 mutations and BRAF fusions, found in both pediatric and adult cancers, are oncogenic drivers that drive constitutive activation of the RAF pathway." (PMID 40111124, 2025). "These targeted therapies, designed to counteract the aberrant activity of mutated BRAF proteins, have yielded significant benefits in certain cancer types, including in HGSOC." (PMID 40141188, 2025).